AKT2 (AKT serine/threonine kinase 2)
Diseases named in the same sentence as AKT2 in open-access papers (continued):
Sharing a sentence is not in itself a finding about the gene and the disease.
ovarian carcinoma (continued). "Correlating changes of CNV and expression can be seen in genes of the ovarian cancer 19q amplicon CCNE1 (r = 0.73) and AKT2 (r = 0.66), suggesting functional variation within the ovarian cancer sample population." (PMID 22174824, 2011). "Overexpression of Akt2 has been found in 20% of human ovarian cancers, and increased Akt2 kinase activity has been found in approximately 30% of ovarian cancers." (PMID 21933447, 2011). "Immunostaining and Western blot analyses using a phospho-Ser-473 Akt antibody that detects the activated form of Akt2 confirmed the frequent activation of Akt2 in ovarian cancer specimens." (PMID 19384426, 2007). "A report showed activation of Akt2 in human primary ovarian cancer and induction of apoptosis by inhibition of PI3K/Akt pathway." (PMID 19384426, 2007). "Applied to six cancer types including renal, breast, pancreatic, head and neck, colorectal, and ovarian cancers, TeaCNV delineated polyclonal architectures and revealed distinct chromatin accessibility patterns driven by CNVs in key driver genes, including AKT2, ZNF217, and SOX2." (PMID 42202285, 2026). "Since Akt2 overexpression is associated with worse outcomes in metastatic tumors, selective inhibition of Akt2 may be helpful, particularly in breast and ovarian cancers." (PMID 40483365, 2025). "AKT2 is linked to metabolic re−programming and invasion, and AKT3 correlates with cancer growth, aggressiveness and chemoresistance in ovarian cancer, suggesting that each isoform may contribute uniquely to the cetrorelix response." (PMID 41458598, 2025). "Since we identified that ABCG1 can phosphorylate AKT2 in ovarian cancer, given the poor curative effects of ovarian cancer, the kinase role of ABCG1 may provide a therapeutic target for ovarian tumorigenesis after further investigations." (PMID 38896016, 2024). "AKT2, a homolog of AKT1, could encode a serine/threonine protein kinase which is largely amplified in pancreatic and ovarian cancers." (PMID 38310291, 2024). "Furthermore, in ovarian cancer, AKT2 amplification/overexpression is correlated with poor prognosis and high-grade disease." (PMID 39614261, 2024). "Notably, the ROS properties of Fc-C8-AmD 8A allows efficient disassembly of its complex with siRNA in ROS–rich environments, thereby inducing specific and significant silencing of the AKT2 gene in ovarian cancer SKOV–3 cells." (PMID 39065632, 2024). "In this way, LIN28B promotes transformation and migration in colon cancer through LGR5, PROM1, and CDX2 mRNAs, promotes stemness and EMT in gastric cancer through NRP-1 mRNA, inhibits apoptosis in ovarian cancer through AKT2 mRNA, and promotes migration in neuroblastoma through MYCN-induced mRNAs." (PMID 37370851, 2023). "In contrast, Akt2 enhanced invasion and metastasis of breast and ovarian carcinoma cells." (PMID 30956761, 2019). "Akt2 inhibition resulted in little reduction in viability of any of the ovarian cancer cell lines." (PMID 27533079, 2016). "Interestingly, inhibition of Akt2 contributed to enhanced ovarian cancer cell proliferation and led to accelerated tumorigenesis in vivo." (PMID 27533079, 2016). "Because altered proliferation is a basic outcome of altered metabolism in cancer cells, we then examined whether AKT2/3 expression affected the glycolytic metabolism of ovarian cancer cells." (PMID 26512921, 2015). "For instance, hypoxia could promote the induction of miR-21 via an Akt2-dependent process in mouse mammary adenocarcinomas and human ovarian carcinomas." (PMID 25839163, 2015). "AKT2 knockdown by RNA interference suppresses cell proliferation and induces apoptosis even increases chemosensitivity in lung adenocarcinoma, malignant gliomas, pancreatic cancer and ovarian cancer." (PMID 25288334, 2014). "Amplification of Akt-2 was observed in human ovarian carcinomas." (PMID 21422497, 2011). "Additionally, AKT2 amplification is more common in high-grade ovarian cancers with poor prognosis." (PMID 40746599, 2025).
ovarian carcinoma (continued). "In addition, AKT2 (AKT Serine/Threonine Kinase 2) upregulation plays a critical role in carcinogenesis, metastasis, and angiogenesis, which can be employed as an anti-cancer target in hepatocellular carcinoma, ovarian cancer, and CC." (PMID 36719624, 2023). "In addition, AKT2 down-regulation sensitised ovarian cancer cells to paclitaxel induced apoptosis and indicated that AKT2 may have a more important role in drug resistance than other members of the AKT family." (PMID 20409325, 2010). "This gene-specific epigenetic regulation parallels previous findings, where JIB-04 modulated AKT2 transcription through H3K27me3, reinforcing its potential as a targeted therapeutic for MECOM-driven ovarian cancers." (PMID 40664642, 2025). "We modulated the PI3K‐AKT pathway in TIL isolated from cervical and ovarian cancer by application of AKT or PI3K inhibitors or CRISPR knockout of AKT1 and/or AKT2, and characterized their effects on TIL phenotype and effector function." (PMID 36028997, 2023). "Frequent amplification of AKT2 was identified in different ovarian cancer cohorts, for example in 18.2% of patients with HGSOC and 10% of patients with advanced ovarian cancer (cohort comprised of 89% HGSOC)." (PMID 35582310, 2021). "The AKT2 gene is often amplified in human cancers, including lung and ovarian cancers while both AKT1 and AKT2 gene amplification has been reported in breast and colorectal cancers." (PMID 34503172, 2021). "Previous studies showed that AKT1 and AKT2, the target genes of PI3K, are overexpressed in breast, gastric and ovarian cancers." (PMID 29175858, 2018). "The constitutive activation in ovarian cancer is a result of amplification of pathway components like PI3K subunits (p110), AKT isoforms (AKT1, AKT2, or AKT3), or members of the mTOR complexes (RICTOR, RAPTOR)." (PMID 27090655, 2016). "Western blotting showed that GSK690693 blocked the miR-29b silencing-induced activation of AKT2/3, HK2 and PKM2, confirming that the miR-29b-AKT axis regulates the activity of key glycolytic enzymes in ovarian cancer cells." (PMID 26512921, 2015). "AKT2 amplification, potentially predicting sensitivity to AKT/MTOR inhibitors, was highly amplified in breast, lung and ovarian cancer samples in our dataset." (PMID 25889064, 2015). "Collectively, these results indicate that AKT2 and AKT3 promoted ovarian cancer progression, probably by enhancing cancerous glycolytic metabolism." (PMID 26512921, 2015). "Western blotting analyses demonstrated that downregulation of Akt2 facilitated a CDDP-induced decrease in mitochondrial AIF content and an increase in nuclear AIF level, and sensitised chemoresistant ovarian cancer cells to CDDP-induced apoptosis." (PMID 18283299, 2008). "Similarly, AKT2 was strongly upregulated in OVCAR-3, in line with its role in ovarian cancer cell survival and drug resistance." (PMID 41035678, 2025). "Additionally, in ovarian cancer, the silencing of HOTTIP led to NLRP1 inflammasome-mediated pyroptosis by focusing on miR-148a-3p/AKT2 axis as a target." (PMID 36281290, 2022). "However, miR-29b negatively regulated both AKT2 and AKT3 expression in both of the selected ovarian cancer cell lines." (PMID 26512921, 2015). "Next, we determined the effects of AKT2 and AKT3 on in vitro ovarian cancer cell proliferation." (PMID 26512921, 2015). "The MTT assay results showed that over-expression of AKT2 and AKT3 enhanced cellular proliferation in the A2780 and SKOV3 ovarian cancer cell lines, while simultaneous over-expression of miR-29b and AKT2/3 led to no statistically significant change in cellular proliferation." (PMID 26512921, 2015). "To explore the involvement of other miRNA/s with a known role in targeting Akt2, we focused on miR-29b, whose gene transcription is positively regulated by Vav1 in acute myeloid leukemia and in MDA-MB-231 cells and that is known to target Akt2 in glioblastoma, gastric and ovarian cancers." (PMID 35743776, 2022).
ovarian carcinoma (continued). "An analysis of the effects of individual AKT isoforms knockdown in ovarian cancer cell lines indicate that the growth suppression shown in the AKT2 KD cell lines could be attributed to the partial inhibition of AKT1 isoform by the AKT2 targeting siRNA." (PMID 33488949, 2020). "While p−AKT (Ser473) can, to some extent, reflect the general pathway activity, the three AKT isoforms (AKT1, AKT2 and AKT3) are not functionally equivalent in ovarian cancer." (PMID 41458598, 2025). "We then examined miR-29b and its latent downstream targets, AKT2 and AKT3 in 30 human ovarian cancer tissues and 30 matched normal ovarian tissues as negative controls." (PMID 26512921, 2015). "For example, the hPGC gene LIN28B plays a very important role in the inhibition of apoptosis through regulation of the AKT2/FOXO3A/BIM axis in ovarian cancer cells, indicating a novel target based on hPGC pluripotency in the diagnosis and therapeutics of ovarian cancer." (PMID 36184610, 2022). "AKT3, but not AKT1 or AKT2, mediated the resistance to apoptosis in BRAF-targeted melanoma cells; promoted anchorage-independent growth in triple negative breast cancer; and controlled the VEGF-induced angiogenesis in ovarian cancer." (PMID 31470874, 2019).
prostate carcinoma (54 papers, 2006 to 2026). A carcinoma that arises from epithelial cells of the prostate gland. "Overexpression or hyperactivation of AKT2 is linked to prostate cancer (PC) development, making it a potential therapeutic target." (PMID 42196210, 2026). "Both AKT1 and AKT2 are required for PTEN-deficient prostate cancer spheroid formation but only AKT2 is essential for tumor spheroid maintenance." (PMID 41408399, 2025). "(2021) exhibited that Akt1- and Akt2-deficient prostate cancer CWR22rv1 cells exhibited an enormous invasive reduction in vitro and in vivo." (PMID 35508982, 2022). "High level of phosphorylated AKT1 is a strong predictor for prostate cancer recurrence while AKT2 is essential for survival of PTEN-deficient prostate tumors." (PMID 26318033, 2015). "Inducible shRNA knockdown of AKT1 or AKT2 in PTEN-deficient prostate cancer cells inhibited the formation of 3D spheroids, suggesting that both AKT isoforms may be required for initial tumour growth." (PMID 28082369, 2017). "Knockdown of AKT2 in PTEN-deficient prostate cancer cells reduces 3D spheroid growth." (PMID 28082369, 2017). "In our MWA screening using 48 antibodies against proteins involved in Akt signaling and cell cycle regulation, we observed that triol caused reduction of Akt1, Akt2, cyclin E2, cyclin B1, phospho-c-Myc Thr58/Ser62, c-Myc, and phospho-Akt Ser473 in all three prostate cancer cell lines." (PMID 23785446, 2013). "It has also been reported that AKT2 ablation stimulated PC-3 cell migration in terms of prostate cancer." (PMID 37179119, 2023). "It was found that overexpression of PHB2 reduced AKT2 expression levels and knockdown of PHB2 increased the expression of AKT2 levels in prostate cancer cells." (PMID 37190120, 2023). "In prostate cancer, whereas silencing Akt2 in spheroids and xenografts induces robust apoptosis, knocking down Akt2 in 2D culture has minimal effect on cell survival." (PMID 34277708, 2021). "In this study, we created prostate cancer CWR22rv1 cells with the double knockout of Akt1 and Akt2 genes through CRISPR/Cas9 method to investigate the effect of Akt in metastasis of prostate cancer." (PMID 33377281, 2021). "In human specimens, we found Akt1 and Akt2 positively correlated, whereas Akt3 inversely correlated, with the overall survival of prostate cancer patients." (PMID 34591413, 2021). "Activating mutations in AKT1–3 are relatively rare in prostate cancer, while gene amplification has been observed in up to 4.5% (AKT1), 2% (AKT2), and 4.7% (AKT3) of prostate cancer cases, respectively." (PMID 33105713, 2020). "Akt1 and Akt2 have also been shown to play opposite roles in regulating migration and invasion in breast cancer while they both inhibit prostate cancer cell migration and invasion." (PMID 31671832, 2019). "MiR-708 targeted AKT2 to inhibit tumor growth of prostate cancer, and miR-203 targeted AKT2 to sensitize colon cancer cells to chemotherapy." (PMID 29051585, 2017). "Recent study reported that AKT2 was activated in prostate cancer cells in response to oxidative stress, resulting in enhanced cell migration and survival." (PMID 29051585, 2017). "The molecular mechanisms how AKT1 and AKT2 regulate proliferation and survival or prostate cancer cells has been extensively studied." (PMID 26318033, 2015). "On the contrary, it has been reported that down-regulation of Akt2 in human prostate cancer cells PC3 enhanced cellular migration and invasion." (PMID 26234648, 2015). "Prior studies showed that blockade of Akt2 decreased IKKα phosphorylation, NF-κB nuclear translocation and cell migration in prostate cancer cells." (PMID 24376747, 2013). "We investigated the correlation between the expression and localisation of Akt-1, Akt-2, Akt-3, phospho-Akt proteins and the clinicopathological parameters in 63 prostate cancer specimens." (PMID 16721361, 2006). "Depletion of mtDNA induces prostate cancer progression through increased PI3 K/Akt2 signaling." (PMID 40210723, 2025).
prostate carcinoma (continued). "In prostate cancer, AKT2 exhibits as a negative regulator of migration function." (PMID 37190120, 2023). "Finally, double KO of Akt1 and Akt2 genes potently decreased prostate cancer cell metastasis in vitro and in vivo." (PMID 35508982, 2022). "Notably, Akt3 mRNA levels are comparable with Akt2 levels (TCGA) in prostate cancer, suggesting a tight post-transcriptional regulation to limit its protein levels in tumors." (PMID 34591413, 2021). "In PTEN-deficient prostate cancer models, downregulation of AKT2, but not AKT1, promoted regression of prostate cancer xenografts through upregulation of p21 and the pro-apoptotic protein Bax, and downregulation of insulin-like growth factor receptor-1." (PMID 33276499, 2020). "AKT1, AKT2, and AKT3 activating mutations are rare in prostate cancer (≤0.9%, predominantly in AKT1 at E17K), whereas AKT1, AKT2, and AKT3 high-level gene amplification that can increase AKT activity is more common, particularly in advanced disease (up to 4.5%, 2%, and 4.7% incidence respectively)." (PMID 32630372, 2020). "In PTEN-deficient prostate cancer, AKT2, but not AKT1, mediates cellular survival and proliferation." (PMID 31470874, 2019). "Moro and colleagues reported that depletion of mtDNA could prevent anoikis and promote migration onto the basement membrane by upregulation of p85 and p110 PI3K subunits, which could result in AKT2 activation and phosphorylation of downstream substrates in prostate cancer." (PMID 38310291, 2024). "In prostate cancer cells, SNHG1 competitively inhibits miR-377-3p expression, leading to AKT2 hyperactivation, which facilitates proliferation and suppresses apoptosis in prostate cancer cells." (PMID 38706912, 2024). "Although previous studies have found that PI3K/AKT phosphorylates MED1 in prostate cancer cells, AKT1 and AKT2 are mainly localized outside of the nucleus." (PMID 35394046, 2022). "AKT is an important target and prognostic marker in prostate cancer and signification overexpression of AKT1, AKT2 and mTOR genes was observed in human prostate cancer samples compared with normal prostate gland tissue." (PMID 36936272, 2022). "The mRNA expression of AKT1, AKT2, and AKT3 are detected in both normal and prostate cancer tissues." (PMID 26318033, 2015). "Transient knockdown of AKT1, AKT2, or AKT3 using siRNA suppresses the proliferation of prostate cancer cells both in vitro and in vivo." (PMID 26318033, 2015). "In sum, our data indicate that PTEN alters AKT isoform dependency such that metastatic prostate cancer progression likely involves substrates preferred by AKT2 and/or AKT3, but not by AKT1." (PMID 37875657, 2024). "In addition, miR-708 was consistently downregulated in prostate cancer cell lines, which resulted in prostate cancer development and progression through regulation of CD44 and Akt2 expression." (PMID 27092874, 2016). "Our observation suggested that AKT3 can regulate the proliferation of prostate cancer cells independent of AKT1 or AKT2." (PMID 26318033, 2015). "Moreover, the annotated genes in the constructed network, such as APC, AXIN1, AKT2, CCND2, CAV1, TLE2 and TCF4, are essential regulatory components of these pathways in prostate cancer." (PMID 23782521, 2013). "KEGG ID "05215 - Prostate Cancer" contains a single known miRNA host (AKT2), and it is not predicted to be targeted by its intronic miRNA (hsa-miR-641)." (PMID 20920310, 2010). "For example, Akt-3 is not expressed in androgen receptor positive prostate cell lines and no constitutive activation of Akt-2 has been observed in prostate cancer cell lines while Akt-1 is constitutively activated in most prostate cancer cell lines." (PMID 16721361, 2006). "The importance of each AKT isoform in PTEN-deficient prostate cancer remains unclear, with some preclinical data suggesting a higher dependency on AKT2 compared to AKT1, yet only deletion of Akt1 and not Akt2 has been shown to suppress prostate neoplasia in a Pten+/− transgenic mouse." (PMID 33105713, 2020).
prostate carcinoma (continued). "The anti-tumorigenic role of miR-708-5p in prostate cancer was not solely due to CD44, as miR-708-5p also targets RAC-beta serine/threonine-protein kinase (AKT2), NNAT, and karyopherin importin subunit alpha-4 (KPNA4) in prostate cancer." (PMID 29050362, 2017). "In addition, knockdown of AKT1 or AKT2, but not AKT3, facilitated cell migration via an increase in activity of integrin β1 in prostate cancer cells." (PMID 26741489, 2016).